U6 (U6 spliceosomal RNA )
Gene: Small nuclear RNA gene on chromosome 15 (65,843,484 to 65,843,558, forward strand). Ensembl gene ENSG00000283249.
Homologues: Orthologues: chimpanzee U6 (99% identical), macaque U6 (81% identical). Paralogues in human: RNU6-838P (84% identical), RNU6-1011P (79% identical), RNU6-1013P (79% identical), RNU6-224P (79% identical), RNU6-558P (79% identical), RNU6-10P (77% identical), RNU6-1290P (77% identical), RNU6-1306P (77% identical), RNU6-132P (77% identical), RNU6-266P (77% identical), RNU6-500P (77% identical), RNU6-71P (77% identical), and 1285 more.